ADAMTS13 (ADAM metallopeptidase with thrombospondin type 1 motif 13)
Diseases named in the same sentence as ADAMTS13 in open-access papers (continued):
Sharing a sentence is not in itself a finding about the gene and the disease.
thrombotic thrombocytopenic purpura (continued). "Clinical manifestations of aHUS are similar to another thrombotic microangiopathy known as thrombotic thrombocytopenic purpura (TTP) which is caused by a decrease in the function of VWF-cleaving protease ADAMTS-13 (A Disintegrin And Metalloproteinase with a ThromboSpondin type 1 motif)." (PMID 23991205, 2013). "Since no clinical symptoms/laboratory findings indicated a malignant or specific autoimmune-mediated disorder, the diagnosis made was thrombotic thrombocytopenic purpura-hemolytic uremic syndrome due to idiopathic combined, autoantibody-mediated ADAMTS-13/factor H deficiency." (PMID 22206706, 2011). "Thrombotic thrombocytopenic purpura (TTP) is a rare, life-threatening hematologic disorder characterized by severe ADAMTS13 deficiency, leading to uncontrolled platelet aggregation, microvascular thrombosis, and multi-organ dysfunction." (PMID 40821327, 2025). "Mutations in the ADAMTS13 gene or, more commonly, autoantibodies against the ADAMTS13 enzyme cause thrombotic thrombocytopenic purpura (TTP)." (PMID 40671815, 2025). "Thrombotic thrombocytopenic purpura (TTP) is a rare hematologic disorder characterized by excessive platelet activation due to ADAMTS13 deficiency, leading to microvascular thrombosis." (PMID 40478853, 2025). "Thrombotic thrombocytopenic purpura (TTP) is a rare and life-threatening disorder due to a severe acquired or inherited ADAMTS13 deficiency." (PMID 40356910, 2025). "Consistent with this role, ADAMTS13 deficiency causes thrombotic thrombocytopenic purpura (TTP) in humans, a disorder characterized by widespread microvascular thrombosis due to uncleaved ULVWF." (PMID 41009700, 2025). "This table summarizes the clinical course of the patient, diagnosed with acquired thrombotic thrombocytopenic purpura (TTP), confirmed by severe ADAMTS13 deficiency and elevated inhibitor levels." (PMID 40821327, 2025). "Deficiency in the activity of plasma ADAMTS13 (<10%) is typical in thrombotic thrombocytopenic purpura (TTP)." (PMID 38785556, 2024). "Thrombotic thrombocytopenic purpura (TTP) is a rare thrombotic microangiopathy caused by reduced activity of the von Willebrand factor-cleaving protease (ADAMTS13), which can be life-threatening." (PMID 38728448, 2024). "Thrombotic thrombocytopenic purpura (TTP) is an uncommon, but potentially disabling or even deadly, thrombotic microangiopathy with a well-studied mechanism of ADAMTS13 deficiency or dysfunction." (PMID 38540234, 2024). "The most common type of TMA is thrombotic thrombocytopenic purpura (TTP), a systemic disorder of microvascular thromboses due to deficiency or inactivation of ADAMTS-13." (PMID 37350773, 2023). "Thrombotic thrombocytopenic purpura (TTP), caused by ADAMTS-13 gene congenital mutation, can also provoke the microvascular thrombosis development of platelet consumption." (PMID 37762167, 2023). "Severe ADAMTS13 deficiency results either from a genetic defect or from polyclonal autoantibodies in acquired thrombotic thrombocytopenic purpura (TTP)." (PMID 37762692, 2023). "Thrombotic thrombocytopenic purpura (TTP) is a thrombotic microangiopathy caused by a hereditary or immune-mediated deficiency of the enzyme ADAMTS13 (a disintegrin and metalloproteinase with a thrombospondin type 1 motif, member 13)." (PMID 37176552, 2023). "The increase in the level of HMWM of VWF due to ADAMTS-13 deficiency causes thrombotic thrombocytopenic purpura (TTP), characterized by microvascular thrombosis and platelet pool depletion." (PMID 36531725, 2022). "It is currently thought that a severe deficiency in ADAMTS13 activity (ADAMTS13:AC) is a specific feature of thrombotic thrombocytopenic purpura (TTP), which is a condition wherein platelet microthrombi are formed in systemic organs." (PMID 35407443, 2022). "Rationale: Thrombotic thrombocytopenic purpura (TTP) is a thrombotic microangiopathy caused by a severe ADAMTS13 activity deficiency." (PMID 35729416, 2022).
thrombotic thrombocytopenic purpura (continued). "Upshaw–Schulman syndrome, or hereditary thrombotic thrombocytopenic purpura (HTTP), is a congenital TTP characterized by a persistent and severe ADAMTS13 deficiency (<10%) caused by homozygous or compound heterozygous pathogenic mutations in the ADAMTS13 gene." (PMID 35163523, 2022). "Thrombotic thrombocytopenic purpura (TTP) is a life-threatening disorder caused by severe ADAMTS13 (a disintegrin and metalloprotease with thrombospondin type 1 repeats, member 13) deficiency (activity <10%)." (PMID 35615090, 2022). "It is assumed that thrombocytopenia and consumptive coagulopathy in severe ICANS patients are due to ADAMTS13 deficiency, which is similar to the mechanism responsible for thrombotic thrombocytopenic purpura (TTP)." (PMID 34794490, 2021). "ADAMTS13 is most commonly known for its deficiency state as part of thrombotic thrombocytopenic purpura (TTP), a prothrombotic disorder." (PMID 34564132, 2021). "Among different forms of TMA, thrombotic thrombocytopenic purpura (TTP) is characterized by deficient ADAMTS-13 activity, with atypical hemolytic uremic syndrome (aHUS) by the dysregulation of the complement system’s alternative pathway." (PMID 34679405, 2021). "The association between ADAMTS13 dysfunction and thrombotic thrombocytopenic purpura (TTP), diabetes, pre-eclampsia, and acute myocardial infarction has been well documented." (PMID 34501736, 2021). "Another disease caused by an abnormal vWF:ADAMTS13 ratio is thrombotic thrombocytopenic purpura (TTP)." (PMID 34208470, 2021). "Significantly elevated levels of VWF are observed in thrombotic thrombocytopenic purpura (TTP), which results from a profound deficiency of ADAMTS13." (PMID 34575297, 2021). "Thrombotic thrombocytopenic purpura (TTP) is a thrombotic microangiopathy caused by a severely reduced activity of the von Willebrand factor-cleaving protease ADAMTS13." (PMID 34796152, 2021). "For example, thrombotic thrombocytopenic purpura is caused by a severe deficiency of von Willebrand cleaving protease (also known as a disintegrin and metalloproteinase with thrombospondin type 1 motif, member 13 (ADAMTS13)), and thus treatment should restore ADAMTS13’s function." (PMID 34300201, 2021). "In addition, a severe deficiency of ADAMTS13 could lead to thrombotic thrombocytopenic purpura (TTP), which is a potentially fatal thrombotic disorder." (PMID 34134634, 2021). "Severe deficiency in ADAMTS13 results in thrombotic thrombocytopenic purpura (TTP), a fatal disorder characterized by systemic microvascular thrombosis." (PMID 33343584, 2020). "On the contrary, increased concentrations of ultra-large multimers of vWF lead to thrombotic thrombocytopenic purpura (TTP), which develops due to a deficiency of ADAMTS-13." (PMID 33096906, 2020). "Moderately low ADAMTS-13 levels increase the risk of ischeamic stroke and very low levels (less than 10%) can cause thrombotic thrombocytopenic purpura (TTP)." (PMID 33352066, 2020). "Hereditary thrombotic thrombocytopenic purpura (TTP) is caused by ADAMTS13 mutations with autosomal recessive inheritance." (PMID 33014938, 2020). "Deficiency of ADAMTS13 causes thrombotic thrombocytopenic purpura (TTP), a disease characterized by overt platelet aggregation through large vWF multimers generating microvascular thrombosis." (PMID 31068896, 2019). "Thrombotic thrombocytopenic purpura (TTP) is an autoimmune disease caused by a deficiency of ADAMTS13, a von Willebrand Factor (vWF)-cleaving metalloprotease." (PMID 31831041, 2019). "Classically, this enzyme has been studied for its association with thrombotic thrombocytopenic purpura (TTP), a life-threatening hematological disease directly linked to severe ADAMTS13 deficiency." (PMID 31731663, 2019). "The acquired form of idiopathic thrombotic thrombocytopenic purpura (TTP) is an autoimmune disease, in which the underlying deficiency of the ADAMTS13 protease is caused by autoantibodies, predominantly of the IgG isotype." (PMID 30061898, 2018).
thrombotic thrombocytopenic purpura (continued). "Thrombotic thrombocytopenic purpura (TTP) results from deficient von Willebrand factor (vWF) cleaving zinc metalloprotease ADAMTS13." (PMID 29728803, 2018). "A severe reduction in ADAMTS13 activity as a result of auto-antibodies is a hallmark of the rare disease thrombotic thrombocytopenic purpura (TTP)." (PMID 28934202, 2017). "Induced substrate promiscuity will be important as ADAMTS‐13 variants are developed as potential therapeutic agents against thrombotic thrombocytopenic purpura (TTP) and other cardiovascular diseases." (PMID 27514025, 2016). "A deficiency in plasma ADAMTS13 activity causes thrombotic thrombocytopenic purpura (TTP), a hereditary or acquired (idiopathic) life-threatening disease." (PMID 27196928, 2016). "Thrombotic thrombocytopenic purpura (TTP) is a life-threatening thrombotic microangiopathy linked to a deficiency in the metalloprotease ADAMTS13." (PMID 27479501, 2016). "Primary ADAMTS13 deficiency caused by defects in the ADAMTS13 gene has been shown to cause Thrombotic thrombocytopenic purpura (TTP)." (PMID 23537039, 2013). "In thrombotic thrombocytopenic purpura (TTP), a deficiency in the ADAMTS13 enzyme leads to the spontaneous formation of platelet-rich microthrombi throughout the microvasculature." (PMID 41535630, 2026). "Investigations at the time revealed a positive hemolytic workup and critically low ADAMTS13 levels (<4%) which led to a working diagnosis of Thrombotic Thrombocytopenic Purpura (TTP)." (PMID 40282368, 2025). "There is also extensive evidence supporting the critical role of routine clinical ADAMTS13 testing in thrombotic thrombocytopenic purpura (TTP) patient diagnostics and prognosis evaluation." (PMID 40725629, 2025). "Jensen Lab data links ADAMTS13 to several diseases, including thrombotic thrombocytopenic purpura, thrombocytopenia, Weill–Marchesani syndrome, hypertension, cerebrovascular disease, carcinoma, and diarrhea." (PMID 40699668, 2025). "A 41 year old female with congenital thrombotic thrombocytopenic purpura (cTTP) underwent a total hip arthroplasty under prophylaxis with recombinant ADAMTS13 (a disintegrin and metalloproteinase with thrombospondin motifs 13)." (PMID 41146274, 2025). "Autoantibodies to ADAMTS13 are at the center of pathology of the immune-mediated thrombotic thrombocytopenic purpura." (PMID 40136473, 2025). "Thrombotic thrombocytopenic purpura (TTP) is a life-threatening disorder caused by a deficiency of a disintegrin and metalloproteinase with a thrombospondin type 1 motif, member 13 (ADAMTS13)." (PMID 41191615, 2025). "Thrombotic thrombocytopenic purpura (TTP) is an uncommon and life-threatening disorder caused by a deficiency of ADAMTS-13, and eventually leads to microangiopathic hemolytic anemia, severe thrombocytopenia, and organ damages." (PMID 40390002, 2025). "Thrombotic thrombocytopenic purpura (TTP) is a rare, life-threatening thrombotic microangiopathy characterized by a profound deficiency in ADAMTS13 activity." (PMID 40827194, 2025). "Fluorescence resonance energy transfer (FRET)–based ADAMTS13 activity assays are critical for the diagnosis of thrombotic thrombocytopenic purpura." (PMID 39657035, 2025). "Classically, these include thrombotic thrombocytopenic purpura (TTP) – a severe deficiency of a disintegrin and metalloproteinase with a thrombospondin type 1 motif, member 13 (ADAMTS13, also known as von Willebrand factor-cleaving protease), and aHUS20." (PMID 39918340, 2025). "Patients with low levels of ADAMTS13 can develop thrombotic thrombocytopenic purpura, characterized by platelet-rich thrombi in the microvasculature." (PMID 39851513, 2025). "Measuring ADAMTS13 activity aids in differentiating PE from other TMAs, such as thrombotic thrombocytopenic purpura (TTP) and hemolytic–uremic syndrome (HUS), and provides insight into endothelial dysfunction, prognosis, and therapeutic decision-making." (PMID 41226469, 2025).
thrombotic thrombocytopenic purpura (continued). "Inadequate functioning of ADAMTS13 can lead to Upshaw–Schulman syndrome, a disorder characterized by thrombotic thrombocytopenic purpura." (PMID 40613041, 2025). "Congenital thrombotic thrombocytopenic purpura (cTTP) results from biallelic pathogenic variants in ADAMTS13, the gene encoding the von Willebrand factor-cleaving protease." (PMID 41458739, 2025). "ADAMTS13 activity was measured and found to be within normal limits, ruling out thrombotic thrombocytopenic purpura (TTP)." (PMID 39583481, 2024). "Thrombotic thrombocytopenic purpura (TTP), also known as Moschcowitz syndrome, is an uncommon hematological disorder caused by deficiency in ADAMTS-13, a von Willebrand factor (VWF) cleaving protein." (PMID 39221447, 2024). "Thrombotic thrombocytopenic purpura (TTP) is a thrombotic microangiopathy characterized by reduced activity of ADAMTS13, a protease responsible for cleaving von Willebrand factor (VWF)." (PMID 38957258, 2024). "ADAMTS-13 deficiency is associated with thrombotic thrombocytopenic purpura (TTP), although there is growing evidence that it is implicated in many other conditions, such as ischemic stroke, myocardial infarction, sepsis, and perioperative thrombotic complications in neonates and infants." (PMID 38399555, 2024). "ADAMTS13 levels in cases of thrombotic microangiopathy or thrombotic thrombocytopenic purpura with polymyositis/dermatomyositis." (PMID 37830409, 2024). "ADAMTS13’s enzymatic activity was >10% in six patients tested for; the other patient presented with platelets of 245 × 109/L, excluding thrombotic thrombocytopenic purpura." (PMID 38250251, 2024). "Insufficient ADAMTS13 activity can lead to unregulated VWF platelet-capturing and is a risk factor for thrombosis including thrombotic thrombocytopenic purpura (TTP), myocardial infarction, stroke, and venous thromboembolism." (PMID 38643218, 2024). "Among the described diseases, a mutation in a single gene caused mastocytosis, thrombotic thrombocytopenic purpura, Gaucher disease, and paroxysmal nocturnal hemoglobinuria (KIT, ADAMTS13, GBA1, and PIG-A genes, respectively)." (PMID 36766791, 2023). "In another form of MAP, the formation of antibodies in the body that block the activity of ADAMTS13 leads to the development of thrombotic thrombocytopenic purpura (TTP)." (PMID 38132876, 2023). "Thrombotic thrombocytopenic purpura (TTP) is a rare and life-threatening thrombotic microangiopathy (TMA) related to a severe ADAMTS13 deficiency, the specific von Willebrand factor (VWF)-cleaving protease." (PMID 37176509, 2023). "Thrombotic thrombocytopenic purpura (TTP) is caused by a reduced activity of the matrix metalloproteinase ADAMTS-13 (a disintegrin and metalloproteinase with a thrombospondin type 1 motif, member 13) due to congenital deficiency or acquired, inhibiting antibodies." (PMID 37337151, 2023). "The primary conditions associated with TMA are linked to two main causes: ADAMTS13 deficiency, leading to Thrombotic Thrombocytopenic Purpura (TTP), and complement dysregulation, leading to complement-mediated TMA (CM-TMA), also named atypical Hemolytic Uremic Syndrome (aHUS)." (PMID 37993892, 2023). "Thrombotic thrombocytopenic purpura is characterized by decreased ADAMTS-13 activity or autoantibodies targeting ADAMTS-13." (PMID 37337151, 2023). "Thrombotic thrombocytopenic purpura impairs the activity of ADAMTS13, a metallopeptidase that contains a thrombospondin motif type 1 member 13)." (PMID 38203218, 2023). "Thrombotic thrombocytopenic purpura (TTP) is a rare and challenging diagnosis that consists of thrombotic microangiopathy due to complete or severe deficiency of ADAMTS13 protease that can present at any age." (PMID 35989804, 2022).
thrombotic thrombocytopenic purpura (continued). "Two major entities with distinct pathophysiology have been recognized: thrombotic thrombocytopenic purpura (TTP) caused by ADAMTS13 (a disintegrin and metalloproteinase with a thrombospondin type 1 motif, member 13) and atypical hemolytic uremic syndrome (aHUS) caused by complement dysregulation." (PMID 35743426, 2022). "Confirmation of a diagnosis of thrombotic thrombocytopenic purpura requires demonstration of very low levels (<10%) of the metalloproteinase ADAMTS13 which in fat embolism syndrome is normal." (PMID 36431152, 2022). "Thrombotic thrombocytopenic purpura (TTP) characterized by microangiopathic hemolytic anemia, thrombocytopenia and signs of organ dysfunction, is due to either congenital or acquired deficiency of ADAMTS13 gene." (PMID 36045839, 2022). "Severe ADAMTS13 deficiency (the VWF cleaving protease) causes accumulation of ultra-large vWF multimers (ULVWF) that can lead to the clinical picture of thrombotic microangiopathy as seen in its most severe form in thrombotic thrombocytopenic purpura (TTP)." (PMID 35551628, 2022). "Studies have shown that recombinant ADAMTS-13 (rh ADAMTS-13) can be used for the treatment of patients with thrombotic thrombocytopenic purpura, reducing AKI in patients." (PMID 34666603, 2021). "These mild or moderately decreased ADAMTS13 activity values excluded thrombotic thrombocytopenic purpura in any patient." (PMID 33572417, 2021). "Except the domains shared by the 19 ADAMTS members, human ADAMTS13 has eight thrombospondin type 1 motifs and has been most reported to affect the progress of thrombotic thrombocytopenic purpura." (PMID 35011462, 2021). "Thrombotic thrombocytopenic purpura (TTP) is a type of thrombotic microangiopathy (TMA) related to a deficiency of ADAMTS13 protein, which could lead to fatal outcomes." (PMID 34877232, 2021). "The deficiency of ADAMTS13, which was also observed in blood samples from COVID-19 patients, results in disseminated microvascular thrombosis, characteristic of thrombotic thrombocytopenic purpura (TTP)." (PMID 34977191, 2021). "Severe ADAMTS13 deficiency is a hallmark of thrombotic thrombocytopenic purpura (TTP)." (PMID 33863735, 2021). "Investigation of the ADAMTS13 protease showed moderately reduced enzyme activity (28%), weakening the diagnostic hypothesis of thrombotic thrombocytopenic purpura (TTP)." (PMID 34648498, 2021). "In a clinical picture similar to thrombotic thrombocytopenic purpura (TTP), inflammatory mediators during sepsis can inhibit or inactivate ADAMTS-13, a metalloprotease whose deficiency leads to microangiopathic thrombosis, end-organ dysfunction and death." (PMID 32154195, 2020). "Greatly diminished levels of ADAMTS13 (< 5%) activity and neurological impairment suggested an initial diagnosis of thrombotic thrombocytopenic purpura (TTP)." (PMID 32471388, 2020). "Severe ADAMTS13 deficiency causes accumulation of ultra-large vWF multimers (ULVWF) leading to the clinical picture of severe thrombotic microangiopathy as seen in thrombotic thrombocytopenic purpura (TTP)." (PMID 32122366, 2020). "Thrombotic thrombocytopenic purpura (TTP) is a hematologic disorder that results in widespread clotting due to a deficiency of a disintegrin and metalloproteinase with a thrombospondin type 1 motif, member 13 (ADAMTS13) protease." (PMID 32411562, 2020). "In thrombotic thrombocytopenic purpura (TTP) patients, an acquired or inherited deficiency of the VWF cleaving protease ADAMTS13 results in accumulation of ultralarge (UL)-VWF multimers." (PMID 30759116, 2019). "The critical role of ADAMTS13 in thrombosis is exemplified by its importance in the pathogenesis of thrombotic thrombocytopenic purpura (TTP)." (PMID 31379722, 2019). "His levels of ADAMTS13 were normal, making a diagnosis of Thrombotic Thrombocytopenic Purpura (TTP) less likely." (PMID 31462210, 2019).